PARP15 (poly(ADP-ribose) polymerase family member 15)
Description:
Mono-ADP-ribosyltransferase that mediates mono-ADP-ribosylation of target proteins. Acts as a negative regulator of transcription.
Synonyms: ARTD7; BAL3; FLJ40597; pART7
Tractability: Small molecule: a structure with a bound ligand is known; a high-quality ligand is known; it has a binding pocket of medium quality. PROTAC: ubiquitination databases record sites on it; a small molecule that binds it is known.
Target class: Enzyme; Transferase
Gene: Protein-coding gene on chromosome 3 (122,577,602 to 122,639,047, forward strand). Ensembl gene ENSG00000173200.
Subcellular location: Nucleus
Gene Ontology:
Molecular function: NAD+ binding; NAD+ poly-ADP-ribosyltransferase activity; NAD+-protein mono-ADP-ribosyltransferase activity; protein binding; transcription corepressor activity; NAD+-protein-aspartate ADP-ribosyltransferase activity; NAD+-protein-glutamate ADP-ribosyltransferase activity
Biological process: negative regulation of transcription by RNA polymerase II; protein poly-ADP-ribosylation; negative regulation of gene expression
Cellular component: cytoplasm; nucleus
Genetic constraint (gnomAD): Loss-of-function variants: 50 observed, 66.38 expected, observed/expected ratio (o/e) 0.75, 90% interval 0.6 to 0.95. The upper end of that interval is the gene's LOEUF score, 0.95, which puts it in group 4 of 6, group 1 being the genes least tolerant of losing a copy. Missense variants: 820 observed, 870.46 expected, observed/expected ratio (o/e) 0.94, 90% interval 0.89 to 1. Synonymous variants: 309 observed, 309.32 expected, observed/expected ratio (o/e) 1, 90% interval 0.91 to 1.1.
Homologues: Orthologues: chimpanzee PARP15 (99% identical), macaque PARP15 (85% identical), dog PARP15 (66% identical), zebrafish parp14rs3 (15% identical), zebrafish si:ch211-244b2.3 (3% identical), zebrafish parp12b (3% identical), zebrafish si:ch211-244b2.4 (2% identical). Paralogues in human: PARP14 (53% identical), PARP9 (18% identical), PARP10 (17% identical), PARP12 (15% identical), TIPARP (14% identical), ZC3HAV1 (14% identical), PARP11 (11% identical), ZC3HAV1L (2% identical).
Diseases named in the same sentence as PARP15 in open-access papers:
PARP15 is named in the same sentence as 21 diseases in open-access papers, as found by Europe PMC text mining. Sharing a sentence is not in itself a finding about the gene and the disease. The quoted sentences say what the papers report.
lymphoma (2 papers, 2019 to 2023). A malignant (clonal) proliferation of B- lymphocytes or T- lymphocytes which involves the lymph nodes, bone marrow and/or extranodal sites. "PARP14 was first described as B-cell aggressive lymphoma protein-2 (BAL2), along with PARP9/BAL1 and PARP15/BAL3, as frequently overexpressed in fatal high-risk lymphoma." (PMID 37507011, 2023).
acute myeloid leukemia (1 paper, 2020). Acute myeloid leukemia (AML) is a group of neoplasms arising from precursor cells committed to the myeloid cell-line differentiation. "PARP15, polymerase family member 15, was originally confirmed as a risk‐related gene in diffuse large B cell lymphomas, and might be potential predictors of hematological toxicity associated with RT for acute myeloid leukemia, cervical cancer, nasopharynx cancer, and tongue cancer." (PMID 33098370, 2020).
B-cell lymphoma (1 paper, 2025). "Along with PARP14, PARP15 is also overexpressed in B-cell lymphoma; although efforts have been made to develop more selective inhibitors targeting PARP15, the effect of its inhibition on tumor progression has not yet been described." (PMID 41463260, 2025).
glioma (1 paper, 2024). A benign or malignant brain and spinal cord tumor that arises from glial cells (astrocytes, oligodendrocytes, ependymal cells). "The results revealed a positive correlation between the expression of genes such as ZC3HAV1, TIPARP, PARP4, PARP14, and PARP15 and the abundance of various immune cell types in gliomas." (PMID 39724285, 2024).
retinal degeneration (1 paper, 2017). Degeneration of the retina. "Our transcriptomic data also revealed an increase in a number of non-apoptotic pathway genes that have been implicated in retinal degeneration, such as a number of poly-ADP-ribose-polymerases (PARP9, PARP14, PARP15) and histone deacetylases (HDAC7, HDAC10, HDAC11)." (PMID 29263354, 2017).
virus infections (1 paper, 2020). "All three macro PARPs are rapidly evolving, and PARP15 has been identified in stress granules; however, direct evidence of their involvement in virus infections is limited." (PMID 32029454, 2020). "No study has identified a role for PARP15 in modulating virus infection or the innate immune response, and thus it will not be discussed further." (PMID 32029454, 2020).
tumor (6 papers, 2019 to 2025). "Notably, PARP4, PARP7, PARP10, PARP11, and PARP15 have been clearly implicated in tumor development and progression, functioning either as oncoproteins with prognostic relevance or, in certain contexts, as tumor-suppressive factors." (PMID 41463260, 2025). "PARP9, PARP11, PARP13, PARP14, and PARP15: The remaining PARP members with MAR activity exhibit a tumor-promoting role." (PMID 41463260, 2025). "These new products have further increased their specificity for other tumor-targeting MARTs, such as PARP14 and PARP15." (PMID 41463260, 2025).
PARP15 also shares sentences with these, for which no sentence is quoted: bipolar disorder (1 paper); cancer (1); cervical cancer (1); colorectal cancer (1); diffuse large B-cell lymphoma (1); Ewing sarcoma (1); gastric cancer (1); Major Depression (1); mood disorder (1); nasopharynx cancer (1); oral cancer (1); rectal cancer (1); salivary gland adenoid cystic carcinoma (1); tongue cancer (1).